BRCA1 (BRCA1 DNA repair associated)
Diseases named in the same sentence as BRCA1 in open-access papers (continued):
Sharing a sentence is not in itself a finding about the gene and the disease.
ovarian carcinoma (continued). "This variant allele produces more mature miR-146a than the wild-type, and the mutant variant has a significantly stronger binding capability to its target BRCA1 and BRCA2 mRNA sequences, which are, themselves, arguably the most studied shared mutations of breast and ovarian cancer." (PMID 27213343, 2016). "The tumor suppressor genes BRCA1 and BRCA2 are the two major breast and ovarian cancer susceptibility genes, and deleterious mutations in these genes have shown to contribute in the pathogenesis of breast/ovarian cancer." (PMID 27818992, 2016). "In conclusion, we found better overall survival for ovarian cancer patients with BRCA1 germline mutations in comparison with patients without these mutations (sporadic) ovarian cancer." (PMID 26753012, 2016). "The distinction between a BRCA1 and a BRCA2 mutation depended on four factors: ovarian cancers favored BRCA1 mutations (p = 0.00011) while male breast cancers (p = 0.0045), prostatic cancers (p = 0.012) and pancreatic cancer (p = 0.022) were more frequent in BRCA2 mutated families." (PMID 26047126, 2015). "miR-9 down-regulated BRCA1 and impeded DNA damage repair in ovarian cancer cells, which could improve chemotherapeutic efficacy." (PMID 25537514, 2015). "Consistently, most breast and ovarian cancers express low, sometimes undetectable, levels of BRCA1." (PMID 25762631, 2015). "However, the roles of lncRNAs in regulating BRCA1/2 and their impact on the prognosis of ovarian cancer have yet to be elucidated, and these warrant detailed research in the future." (PMID 25537514, 2015). "Clinical genetic testing of BRCA1 and BRCA2 is commonly performed to identify specific individuals at risk for breast and ovarian cancers who may benefit from prophylactic therapeutic interventions." (PMID 26246475, 2015). "Mutations in the BRCA1 and BRCA2 genes result in predisposition to breast and ovarian cancers." (PMID 26543556, 2015). "Mutations in BRCA1 and BRCA2 are associated with susceptibility to breast and ovarian cancer." (PMID 25636233, 2015). "BRCA1 and BRCA2 exons were amplified using the Ion AmpliSeq BRCA1/2 Panel and sequenced on the Ion Torrent PGM sequencer in 512 women with familial and/or only early onset breast and/or ovarian cancers who were negative for selected BRCA1/2 mutations." (PMID 25948282, 2015). "By analyzing the expression profiles and GO functional enrichment, we unraveled that carriers of BRCA1/2 alterations and patients with miRNA deregulation shared a common mechanism that affected the prognosis of ovarian cancer treated with platinum-based chemotherapy." (PMID 25537514, 2015). "Understanding this process may lead to insights into other similarly silenced genes like MLH1 in colorectal cancer and BRCA1 in breast and ovarian cancer." (PMID 25747664, 2015). "However, only a small proportion of ovarian cancers exhibit direct genetic or epigenetic alterations in BRCA1/2." (PMID 25537514, 2015). "Consequently, loss of BRCA1 is synthetic lethal to cells harbouring CCNE1 amplifications, and this has recently been validated using inhibition of BRCA1-mediated DNA repair in ovarian cancer cell lines." (PMID 26427375, 2015). "Therefore, in this study, we evaluated the immunohistochemical expression of DBC1 and BRCA1 and their prognostic significance in 104 ovarian carcinomas." (PMID 25823848, 2015). "Individuals (n = 143) recruited were divided into controls, (n = 94): healthy volunteers, (n = 18), high-risk BRCA1/2 negative (n = 53), high-risk BRCA1/2 positive (n = 23) and ovarian cancer cases (n = 49)." (PMID 26301412, 2015).
ovarian carcinoma (continued). "In BRCA1/2 mutation carriers, RRBSO has been shown to be highly protective for ovarian cancer with a cancer risk reduction of 80 % and overall mortality reduction of 60 % following surgery, and is strongly recommended for prevention of ovarian cancers in this population." (PMID 27231565, 2015). "As a significant number of ovarian cancer patients harbour germline BRCA1/BRCA2 mutations, a targeted screen for carriers in this defined population has the potential to improve health management of patients and reduce ovarian cancer risk for their mutation-carrier family members." (PMID 25884701, 2015). "Finally, Blanco and colleagues recently screened a large series of 516 BRCA1/BRCA2-negative patients from breast and/or ovarian cancer families for RAD51C mutations and identified 3 germline pathogenic mutations." (PMID 26075229, 2015). "Deregulation of BRCA1/2-directed miRNA and alteration of BRCA1/2 may share a common mechanism that affects the prognosis of ovarian cancer patients treated with platinum-based chemotherapy." (PMID 25537514, 2015). "Additionally, for some populations the large rearrangements in BRCA1/2 genes have been described in a significant proportion of families with strong breast/ovarian cancer history." (PMID 25948282, 2015). "BRCA1 and BRCA2 germline variant screening using Sanger DNA sequencing or NGS is well established in clinical practice and is used primarily for the determination of hereditary breast and ovarian cancer risk." (PMID 25859162, 2015). "In our analysis none of them significantly altered the ovarian cancer risk in the groups under study, except for the BRCA1+ group where, for heterozygotes for p.Val660Leu polymorphism, a significant increase of cancer risk was found." (PMID 25591549, 2015). "The mutation status may determine the medical management of patients, including annual screening and prophylactic surgery, and genetic testing for BRCA1 and BRCA2 is routinely performed in women with hereditary breast and ovarian cancer risk." (PMID 25948282, 2015). "BRCA1 is a tumor suppressor gene that is involved in the maintenance of genome stability (homologous recombination pathway for double-strand DNA repair) and hence is of paramount importance in hereditary breast and ovarian cancers." (PMID 26092435, 2015). "Furthermore, a relatively low frequency of the other two founder mutations, c.4034delA and c.68_69delAG in our region denotes heterogenity of BRCA1 alterations in Polish patients with ovarian cancer." (PMID 25366421, 2015). "Because DBC1 is involved in the inhibition of BRCA1 and BRCA1/2 status is important in the development and progression of ovarian carcinomas, we investigated the immunohistochemical expression of BRCA1 in ovarian carcinomas." (PMID 25823848, 2015). "Instead, targeted screening for specific BRCA1 mutations performed at the reasonable costs can be offered to all breast or ovarian cancer patients in the Polish population, regardless of the family history or the age of disease onset." (PMID 25948282, 2015). "In-vitro studies of the effect of RB on human ovarian cancer cells with and without BRCA1 mutation have been performed." (PMID 26618054, 2015). "Similarly, despite the inhibitory role of DBC1 for BRCA1, the expression of DBC1 and BRCA1 were positively correlated and both predicted shorter survival of ovarian carcinoma patients." (PMID 26249023, 2015). "Both cases of BRCA1 mutation-related ovarian cancer presented were high-grade tumours with no tubal involvement, diagnosed at younger ages than is typical for the general population, which metastasized to lymph nodes." (PMID 26337050, 2015).
ovarian carcinoma (continued). "Overall, significantly less ovarian cancer is seen in PALB2 families when compared with BRCA1 and BRCA2 families; therefore, it remains to be seen whether ovarian cancer risk is truly increased in individuals who are PALB2 mutation carriers or not." (PMID 26075229, 2015). "Targeted PCR-based genetic testing for BRCA1 and BRCA2 can be performed at a lower cost than full gene testing; however, it may overlook mutations responsible for familial breast and/or ovarian cancers." (PMID 25948282, 2015). "Our work highlights that a proportion of patients with wild-type BRCA1/2 ovarian cancers benefit from platinum-based chemotherapy and that the patients who benefit could be predicted from BRCA1/2-directed miRNA signature." (PMID 25537514, 2015). "Nevertheless, the discovery that miRNAs represent another mechanism that affects the prognosis of ovarian cancer patients with wild-type BRCA1/2 may have important implications for clinical prediction and trial design." (PMID 25537514, 2015). "The connection with BRCA1/2 gene mutations and female breast and ovarian cancers has been widely researched but not so for males." (PMID 26236408, 2015). "For model development, genetic data will involve genetic testing of high penetrance genes associated with hereditary breast and ovarian cancer, BRCA1 and BRCA2, as well as lower penetrance genes associated with ovarian cancer susceptibility, BRIP1, RAD51C and RAD51D." (PMID 25391615, 2015). "Herein, we hypothesized that ovarian cancer patients with wild-type BRCA1/2 but with miRNA deregulation may also have better prognosis than patients with wild-type BRCA1/2 but no deregulation of miRNA." (PMID 25537514, 2015). "Detailed phenotypic and cellular characterization of one patient provided lines of evidence supporting the hypothesis that biallelic BRCA1 (FANCS) mutations cause a new Fanconi anemia subtype associated with increased breast and ovarian cancer susceptibility." (PMID 26596371, 2015). "In ovary cancers, miR-214 is expressed differently between the carriers of the BRCA1 gene mutations and non-carriers; miR-214 is down-regulated in the patients with mutations in the BRCA1 gene." (PMID 25705321, 2015). "UWB1.289 is a BRCA1-null ovarian cancer cell line obtained from a papillary serous tumor." (PMID 25594072, 2014). "BRCA1 and BRCA1a proteins inhibit the growth of human breast and ovarian cancer cells." (PMID 25594072, 2014). "Inherited mutations in BRCA1/BRCA2 for example, increase the risk of breast and ovarian cancer." (PMID 25034939, 2014). "Evidence suggests that in cases of sporadic ovarian cancer promoter hypermethylation, non-somatic mutation is the cause for BRCA1 inactivation." (PMID 24821107, 2014). "In the Iberian Peninsula, which includes mainly Spain and Portugal, large genomic rearrangements (LGRs) of BRCA1 and BRCA2 have respectively been found in up to 2.33% and 8.4% of families with hereditary breast and/or ovarian cancer (HBOC) that lack point mutations and small indels." (PMID 24686251, 2014). "Thus, a negative regulation loop between Aur A/B and BRCA1/2 was uncovered in both pancreatic and ovarian cancer cell lines." (PMID 24775809, 2014). "The discrepancy in previous studies indicated that not all ovarian cancer cells with BRCA1/2 mutation exhibited HR deficiency." (PMID 25437005, 2014). "A patient diagnosed with ovarian cancer in her 4th decade and a strong family history of breast and ovarian cancer had previously tested negative for deleterious BRCA1 and BRCA2 mutations by another commercial lab." (PMID 24830819, 2014). "Unlike BRCA1/2 mutation carriers, no elevated risk of ovarian cancer or any other cancer was found in these females." (PMID 24667084, 2014). "Furthermore, it was found that many BRCA1 mutant ovarian cancer patients were resistant to chemotherapy agents that induce DSBs." (PMID 25437005, 2014).
ovarian carcinoma (continued). "CA-125 was established as a prognostic marker in cancer, specifically in ovarian carcinoma and the present results indicated that BRCA1 methylation and CA-125 levels, in combination, may be used as biomarkers for the diagnosis and prognosis of EOC." (PMID 24944674, 2014). "BRCA1 and BRCA2 are also mutated in patients with ovarian cancer." (PMID 25051360, 2014). "Clinical and pathological features of BRCA1 c.190T>C related ovarian cancer cases." (PMID 24516540, 2014). "BRCA1 is a key breast and ovarian cancer suppressor involved in DSB repair." (PMID 25400221, 2014). "The role of sex hormones in ovarian cancer development is complex however, and early evidence suggests that endocrine function may differ in BRCA1 heterozygotes." (PMID 24478985, 2014). "Characteristics of studies of patients of ovarian cancer with low BRCA1 expression measured by IHC." (PMID 24788697, 2014). "In sporadic forms, BRCA1/2 somatic mutations are not very common but still are a significant causative gene defect, as shown in extensive genomic analyses of ovarian carcinoma by the Cancer Genome Atlas Research Network." (PMID 25136623, 2014). "The silencing of BRCA1 gene trough promoter hypermethylation may occur in sporadic breast and ovarian cancers." (PMID 25136623, 2014). "BRCA1—a breast and ovarian cancer suppressor gene—promotes genome integrity." (PMID 25400221, 2014). "Why here reported ovarian cancer patients without BRCA1/2 mutations and Israeli controls present with such an unusually high, and apparently elevated prevalence over average populations, of low FMR1 alleles is unclear." (PMID 25036526, 2014). "However, the regulatory effects of BRCA1 on GR were only observed in ovarian cancer cells; 293 T cells were insensitive to the knockdown or overexpression of BRCA1." (PMID 24629067, 2014). "Besides the BRCA1/2 genotypes, the TCGA ovarian cancer paper showed that gene expression-based sample clusters are also associated with the survival outcomes." (PMID 25390899, 2014). "PALB2 mutation screening identifies a small, but significant number of mutations in BRCA1/2 -negative breast and/or ovarian cancer families." (PMID 25225577, 2014). "Only one wild allele of BRCA1 or BRCA2 is sufficient for DNA repair mechanism, so as in Knudson's model, and additional somatic loss of the wild-type allele is necessary to develop ovarian carcinoma in women with a germline BRCA mutation." (PMID 24063014, 2013). "Of these, the 4q32.2 locus was associated with ovarian cancer risk for BRCA1 carriers but not for BRCA2 carriers or in the general population." (PMID 23544013, 2013). "Recent histopathological studies on early stage lesions of ovarian cancer in BRCA1 or BRCA2 carriers have suggested that the primary origin of high-grade serous ovarian cancer is the fallopian tube, implicating both genes as key players in the fallopian differentiation." (PMID 23536787, 2013). "Notable in this pedigree is that lack of ovarian cancer cases typified by BRCA1 or BRCA2 mutation carrier families." (PMID 23302520, 2013). "Using PARP inhibitors in such a scenario is based on the idea that there is a HR DNA repair defect, but no germline BRCA1/2 mutation in up to 50% of ovarian cancers." (PMID 24098868, 2013). "One important consideration is whether differentials in response to platinum-based chemotherapy between BRCA1- and BRCA2-mutated ovarian cancers observed in recent studies may also be true with respect to the therapeutic response elicited by PARP inhibitors." (PMID 24349831, 2013).
ovarian carcinoma (continued). "A number of women without a family history of early onset breast or ovarian cancer discovered that they carry a BRCA1 or BRCA2 mutation that conveys a high risk." (PMID 23638402, 2013). "Since ovarian cancers with mutations in BRCA1 or BRCA2 are more sensitive to platinum-containing chemotherapy, we asked whether the total number of somatic mutations in ovarian cancer predicts sensitivity to chemotherapy and clinical outcome." (PMID 24265793, 2013). "RAD51C was investigated as a possible breast and ovarian cancer susceptibility gene in 1100 high-risk families, who were previously tested negative for BRCA1 and BRCA2 mutations." (PMID 23586058, 2013). "Of the 29 patients who developed both breast and ovarian cancer and had a family history 14/29 (48.3%) carried a BRCA1 mutation, whereas from those that had no clear family history 11/24 (45.8%) carried a BRCA1 mutation." (PMID 23536787, 2013). "BRCA1 is a multi-functional protein but it is not fully understood which function(s) is (are) most important for tumor suppression, nor is it clear why BRCA1-mutations confer a high risk for breast and ovarian cancers and not a broad spectrum of tumor types." (PMID 23802008, 2013). "Real-time PCR and immunohistochemical analysis showed that the levels of EGFR mRNA and protein were increased in non-mutated and BRCA1-mutated ovarian cancer compared with their adjacent normal tissue." (PMID 24321281, 2013). "If the other BRCA1 gene (inherited from our other parent) breaks (mutates), we no longer have protection against breast or ovarian cancer." (PMID 25032017, 2013). "All of this may improve our understanding of the basic molecular mechanism of BRCA1-related ovarian cancer." (PMID 24321324, 2013). "The BRCA1 and BRCA2 mutations increase the susceptibility to breast or ovarian cancer, and it has been estimated that the probability of developing these forms of cancer is between 30 and 80% in individuals carrying hetero- or homozygous mutations in these genes." (PMID 23675572, 2013). "It is unclear why BRCA1 methylation, even coupled with high Nmut, does not translate into the same survival benefit seen in ovarian cancer with BRCA mutations and high Nmut." (PMID 24265793, 2013). "BRCA1/BRCA2 mutation-negative Spanish high risk breast/ovarian cancer families with pancreatic cancer cases." (PMID 23935836, 2013). "We studied 145 unrelated affected index patients from Pakistani breast and/or ovarian cancer families all of whom have previously been tested and found to be negative for BRCA1/2 germ line mutations (Group 1)." (PMID 23806170, 2013). "We utilised a cohort of well-characterised BRCA1/2-founder mutation-negative individuals from 84 Finnish hereditary breast and/or ovarian cancer families who had been previously screened for variations in seven known BC genes." (PMID 23967248, 2013). "BRCA1 knockdown was an effective way to activate EGFR expression in ovarian cancer cells." (PMID 24321281, 2013). "Instead, pediatric ovarian cancers are associated with a number of hereditary and non-hereditary syndromes distinct from the syndromes of breast/ovarian cancer linked to BRCA1/2." (PMID 23641362, 2013). "To date, although the exact cause of ovarian cancer is not clear, BRCA1 and BRCA 2 mutations are the only known causes of hereditary ovarian cancer." (PMID 23442605, 2013). "Pegylated liposomal doxorubicin may be considered as a promising treatment option for BRCA1/2-related ovarian cancer after the failure of platinum-containing therapy." (PMID 23548133, 2013). "To identify further cancer risk-modifying loci, we performed a multi-stage GWAS of 11,705 BRCA1 carriers (of whom 5,920 were diagnosed with breast and 1,839 were diagnosed with ovarian cancer), with a further replication in an additional sample of 2,646 BRCA1 carriers." (PMID 23544013, 2013).